SLC1A7 (solute carrier family 1 member 7)
Description:
Sodium-dependent, high-affinity amino acid transporter that mediates the uptake of L-glutamate and also L-aspartate and D-aspartate. Functions as a symporter that transports one amino acid molecule together with two or three Na(+) ions and one proton, in parallel with the counter-transport of one K(+) ion. Acts primarily as an inhibitory glutamate-gated chloride channel being a major inhibitory presynaptic receptor at mammalian rod bipolar cell axon terminals. Glutamate binding gates a large Cl(-) conductance that mediates inhibition, affecting visual processing in the retina (By similarity).
Synonyms: EAAT5; AAAT
Tractability: Small molecule: it belongs to a druggable protein family. Antibody: its Gene Ontology location is reachable by antibodies, with high confidence; UniProt places it where antibodies can reach, with medium confidence; UniProt predicts a signal peptide or a membrane-spanning region.
Gene: Protein-coding gene on chromosome 1 (53,087,179 to 53,142,638, reverse strand). Ensembl gene ENSG00000162383.
Subcellular location: Photoreceptor inner segment membrane; Synaptic cell membrane
Pathways (Reactome):
Neuronal System: Glutamate Neurotransmitter Release Cycle
Transport of small molecules: SLC-mediated transport of amino acids
Gene Ontology:
Molecular function: glutamate:sodium symporter activity; protein binding; extracellularly glutamate-gated chloride channel activity; high-affinity L-glutamate transmembrane transporter activity; L-glutamate transmembrane transporter activity; neutral L-amino acid transmembrane transporter activity; symporter activity
Biological process: neurotransmitter uptake; amino acid transport; chloride transmembrane transport; dicarboxylic acid transport; L-glutamate transmembrane transport; neurotransmitter transport; excitatory postsynaptic potential; import into cell; neutral amino acid transport
Cellular component: plasma membrane; synaptic membrane; membrane; postsynapse
Genetic constraint (gnomAD): Loss-of-function variants: 35 observed, 41.4 expected, observed/expected ratio (o/e) 0.85, 90% interval 0.64 to 1.12. The upper end of that interval is the gene's LOEUF score, 1.12, which puts it in group 4 of 6, group 1 being the genes least tolerant of losing a copy. Missense variants: 704 observed, 742.19 expected, observed/expected ratio (o/e) 0.95, 90% interval 0.89 to 1.01. Synonymous variants: 311 observed, 316.68 expected, observed/expected ratio (o/e) 0.98, 90% interval 0.89 to 1.08.
Homologues: Orthologues: chimpanzee SLC1A7 (99% identical), macaque SLC1A7 (98% identical), guinea pig SLC1A7 (94% identical), dog SLC1A7 (93% identical), pig SLC1A7 (93% identical), mouse Slc1a7 (92% identical), rat Slc1a7 (92% identical), tropical clawed frog slc1a7 (81% identical), zebrafish slc1a7a (74% identical), zebrafish slc1a7b (73% identical). Paralogues in human: SLC1A3 (49% identical), SLC1A6 (47% identical), SLC1A1 (44% identical), SLC1A2 (42% identical), SLC1A4 (38% identical), SLC1A5 (36% identical).
Diseases named in the same sentence as SLC1A7 in open-access papers:
SLC1A7 is named in the same sentence as 11 diseases in open-access papers, as found by Europe PMC text mining. Sharing a sentence is not in itself a finding about the gene and the disease. The quoted sentences say what the papers report.
Anxiety (1 paper, 2019). Intense feelings of nervousness, tension, or panic often arise in response to interpersonal stresses. "The behavioral score of anxiety-like behavior of the adult males—but not females—yielded 5 significant correlations with Slc1a7, 9530052E02Rik, Itgb7, Tiam2, and Tspo (adjusted p = 0.048)." (PMID 30655507, 2019).
cancer (2 papers, 2010 to 2020). A tumor composed of atypical neoplastic, often pleomorphic cells that invade other tissues. "Looking at the top 5 coding mutations, for example, we noted that corresponding genes (FES, TNFSF15, MSRB1, HRAS, and SLC1A7) have all been experimentally implicated in cancer as drivers." (PMID 32859160, 2020).
mental illnesses (1 paper, 2021). "SLC1A7 and DISC1 are also susceptibility genes for mental illnesses." (PMID 33568133, 2021).
tumor (1 paper, 2023). "However, from a prognostic perspective, CD5, SLCO1B1, and CD79A have been demonstrated to have protective value in various tumors, whereas ETV5, FZD7, SNX7, and SLC1A7 are involved in tumor progression." (PMID 37680641, 2023).
SLC1A7 also shares sentences with these, for which no sentence is quoted: bipolar disorder (1 paper); diabetic retinopathy (1); infection (1); major depressive disorder (1); multiple sclerosis (1); nervous system diseases (1); systemic lupus erythematosus (1).